CKAP4 (cytoskeleton associated protein 4)
Diseases named in the same sentence as CKAP4 in open-access papers (continued):
Sharing a sentence is not in itself a finding about the gene and the disease.
tumor (continued). "The two results were further confirmed in vivo by comparing xenograft tumor growth between CKAP4-depeleted TE-8 cells or KYSE960 cells and control cells, respectively." (PMID 33614703, 2020). "One of the antibodies, only reacting with tumor cells in lung tumor tissues, was recognized to interact with CKAP4." (PMID 33614703, 2020). "Palmitoyl acyltransferase DHHC2, which is a putative tumor suppressor, modifies Cys100 of CKAP4 and contributes to the localization of CKAP4 on the plasma membrane." (PMID 33614703, 2020). "This review discusses the publications that describe CKAP4 in various diseases, especially on tumor promotion and suppression, and provides a detailed discussion on the discrepancy." (PMID 33614703, 2020). "In 47 PDAC patients, including 27 resectable and 20 unresectable cases, the serum levels of CKAP4 were obviously higher in unresectable cases than in resectable ones, suggesting serological CKAP4 correlated with tumor stages." (PMID 33614703, 2020). "In HCC, it revealed that CKAP4 expression was high while its palmitoyl-transferase DHHC2 expression was low in most tumor tissues, and high expression of CKAP4 and DHHC2 was positive with prognosis." (PMID 33614703, 2020). "We found that overexpression of MYCT1 abolished CKAP4‐mediated up‐regulation of E‐cadherin and CKAP4 interference‐induced tumour cell migration." (PMID 26710964, 2016). "Indeed, anti-CKAP4 monoclonal antibodies have shown promising results in inhibiting tumor growth, indicating their potential utility in targeted therapy." (PMID 41149482, 2025). "Indeed, in stressed tumor CKAP4 showed evident phase separation, and it led to a dramatic distant metastasis to the liver, CKAP4 exhibited a significant effect." (PMID 39528501, 2024). "Taken together, our data showed that CKAP4 could sense and respond to solid stress at both cell level and tissue level through molecular condensation, suggesting its importance in tumor progression." (PMID 39528501, 2024). "CKAP4 functions as a receptor for Dickkopf1 and participates in tumor progression." (PMID 38052924, 2023). "Furthermore, DKK1 and CKAP4 were found in tumor lesions in more than 70% of lung squamous cell carcinoma patients." (PMID 35355709, 2022). "Interestingly, CKAP4 has been recently recognized as a serological marker of several tumors and CKAP4 is expected to be a tumor therapeutic target." (PMID 33614703, 2020). "Moreover, high expression of CKAP4 inhibited the growth of xenograft tumor and the metastatic potential of HCC in nude mice." (PMID 33614703, 2020). "Therefore, in further study, the function of CKAP4 in special type of tumor should be analyzed individually." (PMID 33614703, 2020). "The DKK1 receptor and cytoskeleton-associated protein 4 (CKAP4) are expressed in tumor cells, suggesting that the inhibition of DKK family members and DKK1–CKAP4 interactions can be examined as a potential therapeutic target, but further studies are still needed to validate this approach." (PMID 31684152, 2019). "However, the role of CKAP4 is still controversial in tumor biology, which may be related to different signal transduction pathways mediated by binding to different ligands in various microenvironments." (PMID 33614703, 2020). "Therefore, large samples and multicenter studies are needed to confirm whether CKAP4 can be used as a serologic marker to diagnose tumor and predict prognosis." (PMID 33614703, 2020). "Therefore, CKAP4 is expected to become a novel serological marker for tumor diagnosis." (PMID 33614703, 2020). "We suppose that MYCT1 might enhance the tumour cell migration through inhibiting CKAP4 function." (PMID 26710964, 2016). "The molecular mechanisms by which DKK1 promotes tumor progression, metastasis, and immune evasion are driven by its interaction with cell-surface receptors, specifically LRP5/6 and CKAP4." (PMID 42123366, 2026).
tumor (continued). "The interaction between DKK1 and CKAP4 is essential for the proliferation of HCC cells, suggesting that the binding of these molecules is a critical step in tumor progression." (PMID 41149482, 2025). "Anti-CKAP4 antibodies block DKK1 binding, suppressing AKT activity and inhibiting tumor growth in xenograft models." (PMID 41149482, 2025). "Knockdown of CKAP4 inhibited cell proliferation and suppressed Akt activity in vitro in PDAC and ESCC, while it also impeded tumor formation in vivo." (PMID 41149482, 2025). "CKAP4′s high expression in ESCC together with activation of the axis DKK1-CKAP4 or DKK3-CKAP4 leading to downstream Akt-activation enhances ESCC cell proliferation and tumor progression, resulting in poorer overall prognosis." (PMID 41149482, 2025). "In CRC, sh-RNAs targeting CKAP4 have the ability to suppress both DKK1 and Akt levels, and tumor and colony formation." (PMID 41149482, 2025). "IHC results elucidated the expression patterns of CKAP4 and PLOD2 in HCC tumour tissues and surrounding areas, providing visual evidence of their upregulation." (PMID 40673276, 2025). "The role of DKK1 in fostering immunosuppression is partly facilitated through its interaction with CKAP4 on macrophages, activating the PI3K-Akt pathway and promoting an M2 phenotype that suppresses anti-tumor immunity." (PMID 39788945, 2025). "In 119 tumor lesions of ESCC, there were close to 40% of cases positive for both DKK1 and CKAP4, about 30% of cases positive for either CKAP4 or DKK1, and approximate 30% negative for both." (PMID 33614703, 2020). "Among the upregulated genes in the tumors compared to those in the normal tissue, we found CKAP4, DUSP1, PAX8, AP1M2, C-KIT and NOTCH3, with NOTCH3 being the only gene that was upregulated in all tumor types." (PMID 31159852, 2019). "Moreover, anti-CKAP4 antibodies inhibited HCC growth and reduced HCC tumor size and weight, while their anti-tumor effects were significantly enhanced when combined with lenvatinib, a multikinase inhibitor commonly used in HCC treatment." (PMID 41149482, 2025). "The correlation between CKAP4 expression in tumor cells and poor RFS with advanced clinicopathological characteristics in the present study may represent the interaction of CKAP4 and DKK1." (PMID 40282454, 2025). "The binding DKK1 and CKAP4 can trigger downstream signaling pathways, including PI3K/AKT and MAPK1/3, thereby influencing cellular functions and promoting the proliferation, migration, and invasion of tumor cells." (PMID 37835450, 2023). "It is possible that hypopalmitoylation of both CKAP4 and CD9 may increase tumor or metastatic behavior." (PMID 23457560, 2013). "Furthermore, CKAP4′s interaction with DKK1 is shown to play a significant role in ESCC cell proliferation and tumor formation via protein kinase B (Akt) phosphorylation, while the presence of both molecules is the necessary condition for their mechanism of action." (PMID 41149482, 2025). "Moreover, an anti-CKAP4 polyclonal antibody blocked DKK3-CKAP4 binding, inhibiting tumor growth." (PMID 41149482, 2025). "Indeed, expression of CKAP4-WT but not CKAP4-C100S rescued the reduction in tumor growth induced by knockout of CKAP4." (PMID 37759431, 2023).
infection (5 papers, 2020 to 2025). The state of being infected such as from the introduction of a foreign agent such as serum, vaccine, antigenic substance or organism. "At 24 h post infection, we found approximately 70% of cells with distinct perinuclear capsid distribution (green channel) defined by CKAP4 localization (red channel)." (PMID 40431628, 2025). "Though interesting, and although we could show that CKAP4 can be ubiquitinated by SneRING in an in vitro reaction, these theories must be confirmed by analyzing whether any of these proteins are ubiquitinated upon SneRING expression or during infection." (PMID 41196921, 2025). "Interestingly, Mic60/IMMT, CKAP4, and Erlin2 were primarily present in the pull-downs of Sne-infected samples expressing FLAG-tagged SneRING, indicating that active infection is necessary for the interactions with SneRING to take place." (PMID 41196921, 2025).
gastrointestinal tumors (1 paper, 2023). "There have been several studies on the DKK1/CKAP4 axis in gastrointestinal tumors." (PMID 37835450, 2023).
CKAP4 also shares sentences with these, for which no sentence is quoted: oral squamous cell carcinoma (4 papers); ischemic stroke (2); kidney disease (2); septic shock (2); acute kidney injury (1); acute myeloid leukemia (1); adenocarcinoma (1); Alzheimer disease (1); atrophic gastritis (1); brain tumor (1); dengue (1); diffuse large B-cell lymphoma (1); Esophageal Neoplasms (1); heart failure (1); hematological cancers (1); hepatitis C (1); Infertility (1); liver transplant (1); malignant pleural mesothelioma (1); metastatic tumors (1); neuroblastoma (1); non-small cell lung carcinoma (1); Obesity (1); osteosarcoma (1); squamous cell carcinoma (1); systemic inflammatory response syndrome (1); urothelial carcinoma (1); viral infections (1).